CDX2 (caudal type homeobox 2)
Diseases named in the same sentence as CDX2 in open-access papers (continued):
Sharing a sentence is not in itself a finding about the gene and the disease.
gastric cancer (continued). "In addition, a trend for fewer patients with early-onset gastric cancer (diagnosed at age younger than 50 years old) at presentation was observed in the group with induced CDX2 expression (Fisher’s exact test p = 0.09)." (PMID 39768557, 2024). "The most frequently amplified oncogenes in gastric cancers, including MYC, ERBB2 (encoding for HER2), and CCNE1 (encoding for cyclin E), showed higher prevalence in the higher CDX2-expressing group, which was statistically significant for MYC (Fisher’s exact test p = 0.008)." (PMID 39768557, 2024). "Notably, gastric cancer cell lines, which often express CDX2 and other intestine-related genes, were downregulated under low pH conditions." (PMID 37962678, 2024). "CDX2, a transcription factor of hindgut specification, is induced in several gastric cancers, especially with intestinal differentiation, and could be helpful for defining sub-types with particular characteristics." (PMID 39768557, 2024). "Moreover, as observed in gastric cancer patients, methylation of Cdx2 with consecutive downregulation of gene expression is predominantly found to be increased in males, possibly being ascribed to gender-specific host factors such as estrogens." (PMID 35053658, 2022). "Second, CDX2 upregulated Reg IV expression in gastric cancer cells." (PMID 33639844, 2021). "Additionally, CDX2 overexpression inhibited proliferation, migration, and invasion in human gastric cancer cell lines (MGC-803, MKN-45, and BGC-823)." (PMID 33639844, 2021). "Fourth, CDX2 promoted migration and invasion of gastric cancer cells." (PMID 33639844, 2021). "Collectively, although CDX2 and Reg IV are involved in the development and progression of gastric cancer, the regulatory correlation between CDX2 and Reg IV in gastric cancer remains unclear." (PMID 33639844, 2021). "Several studies have reported that CDX2 acts as a tumor suppressor in gastric cancer." (PMID 33639844, 2021). "Previous studies showed that CDX2 may be an upstream regulator of Reg IV expression in gastric cancer, and our previous report showed that Reg IV upregulated SOX9 expression and enhanced cell migration and invasion in gastric cancer cells." (PMID 33639844, 2021). "The most extensively researched homeobox genes in stomach cancer are CDX2 and CDX1." (PMID 34206291, 2021). "These contradictory findings imply that CDX2 plays a complex regulatory role in gastric cancer." (PMID 33639844, 2021). "Other results suggested that CDX2 might also play an important role in other cancer types and in particular in stomach cancer (STAD)." (PMID 34430923, 2021). "In addition, the expression of CDX2 protein has the highest values in complete IM, followed by incomplete IM and gastric cancer, which has the lowest values." (PMID 34206291, 2021). "When SOX9 is increased to a certain level, it may conversely suppress the expression of CDX2 and Reg IV, resulting in a reduction of migration and invasion of gastric cancer cells." (PMID 33639844, 2021). "Moreover, CDX2 promoted the migration and invasion of gastric cancer cells (AGS and MKN-45) through upregulation of Reg IV expression." (PMID 33639844, 2021). "Moreover, it was shown that the expression of CDX2 in gastric cancer is mainly due to promoter hypermethylation." (PMID 34206291, 2021). "Down-regulation of CDX2 expression promoted gastric cancer cell proliferation." (PMID 30631044, 2019). "CDX2-positive gastric cancer is more prevalent in differentiated type gastric cancers." (PMID 31040910, 2019). "In support of our data, miR-9 has also been reported as a regulator of CDX2 expression in gastric cancer, where CDX2 expression may be regulated through other mechanisms such as the oncogenic ras-activated PKC pathway or CDX2 mutations." (PMID 31783700, 2019). "CDX2 is rarely positive in gastric carcinomas, as in our cases." (PMID 31205468, 2019).
gastric cancer (continued). "The role of CDX2 in gastric cancer has been reported as responsible for the proliferation and differentiation of intestinal type of epithelial cells by controlling transcriptional activation of intestine specific proteins, like sucrase-isomaltase, carbonic anhydrase I, or Mucin 2 (MUC2)." (PMID 29867026, 2018). "This may explain an important aspect of the mechanism by which the overexpression of CDX2 contributes to the suppression of gastric cancer cell growth." (PMID 25738600, 2015). "The CDX2 regulatory network is intricate and remains to be fully elucidated in gastric cancer." (PMID 25738600, 2015). "In gastric cancer, miR-9 targets CDX2 (caudal-related homeobox) to promote cell proliferation." (PMID 26593208, 2015). "Similarly, CDX2 was reported as a prognostic factor that acted as a marker of good outcome in patients with gastric cancer." (PMID 24228025, 2013). "Our previous study also showed that both the upregulation and downregulation of Cdx2 could suppress human gastric cancer progression." (PMID 23181722, 2012). "Interestingly, some studies have examined Cdx2 in gastric cancer using methods other than immunohistochemistry (reverse transcription-PCR, immunofluorescence or western blot)." (PMID 23181722, 2012). "In other word, the incidence of Cdx2-positive expression was significantly higher in males than in females, significantly higher in the well and moderately type gastric cancer than poorly differentiated type, and significantly lower in carcinomas in stages III+IV than in stage I+II." (PMID 23181722, 2012). "Cdx2 is a homeobox domain-containing transcription factor that is important in the development and differentiation of the intestinal cells, and served as a potential biomarker of tumor progression in early intestinal-type gastric cancer." (PMID 23181722, 2012). "Missing information may reflect “negative” or more conservative association of Cdx2 with clinicopathological parameters or 5-year survival rate that could reduce the significance of Cdx2 expression as a predictor of of outcome in gastric cancer." (PMID 23181722, 2012). "The transcription factor Cdx2 is a member of the caudal-related homeobox gene family, which plays an important role in the proliferation and differentiation of intestinal epithelial cells, and is involved in the development and progression of gastric cancer." (PMID 23181722, 2012). "Whether Cdx2-positive expression could be considered as a prognostic factor for gastric cancer patients is still in dispute at the present time." (PMID 23181722, 2012). "In conclusion, our meta-analysis suggests that Cdx2 expression might be a good prognostic factor for survival in patients with gastric cancer, if detected by immunochemistry." (PMID 23181722, 2012). "In the present study, Cdx2 expression was increased in gastric cancers with male gender." (PMID 23181722, 2012). "Cdx2 was bound to the Cdx1 promoter region in the intestinal metaplasia and the normal intestine, and upregulated the transcriptional activity of the Cdx1 gene in the human gastric carcinoma." (PMID 23181722, 2012). "However, CDX2 expression was also found in gastric carcinoma, and other carcinomas with intestinal-type morphology." (PMID 22268990, 2012). "Among the CDX2 positive gastric carcinomas (36/59), reactivity was focal in 22 cases (22/36, 61%)." (PMID 22268990, 2012). "They indicated that Cdx2 was an independent prognostic indicator for gastric carcinoma." (PMID 23181722, 2012). "OPN combined with CDX2 appears to predict survival of advanced gastric cancer patients, and CDX2 may be a transcription factor that modulates the expression of osteopontin." (PMID 21992455, 2011). "In addition, the prognosis of gastric carcinoma patients with CDX2 positive expression is significantly better than that in patients with CDX2 negative expression." (PMID 22074191, 2011).
gastric cancer (continued). "In this regard, PTEN activity has recently been shown to induce an intestinal differentiation of gastric carcinomas by increasing CDX2, claudin-3 and claudin-4 expression, hence supporting this hypothesis." (PMID 21203412, 2010). "They reported that Cdx1 and Cdx2 expression was independent of the type of IM and of gastric carcinoma, and that it was significantly associated with expression of the intestinal mucin Muc2." (PMID 19412438, 2007). "The proportion of pathogenic mutations in the examined WNT/APC/β-catenin pathway genes of the MSI-high subgroup of CDX2-induced, SOX2-suppressed gastric cancers was 28.6% (22 of 77 mutations), while the rest were of unknown significance, according to the evaluation in the OncoKB knowledgebase." (PMID 40149431, 2025). "However, others consider CDX2 an oncogene in gastric cancer." (PMID 33639844, 2021). "Consequently, CDX2 may have considerable potential as a novel therapeutic target for gastric cancer." (PMID 33639844, 2021). "Therefore, we speculate that CDX2 may regulate the migration and invasion of gastric cancer cells through Reg IV/SOX9 signaling." (PMID 33639844, 2021). "Therefore, control of the cell cycle may be an important mechanism in the suppression of tumor growth by CDX2 in gastric cancer." (PMID 25738600, 2015). "Therefore, lentiviral vector-mediated overexpression of CDX2 may be used as a potent and specific therapeutic tool for the treatment of gastric cancer." (PMID 25738600, 2015). "Gastric cancer (GC) patients who were positive for caudal type homeobox transcription factor 2 (CDX2) expression showed a higher survival rate compared with those who were CDX2 negative, which suggests that CDX2 performs a tumor suppressor role." (PMID 23408490, 2013). "Thus, this meta-analysis was conducted to determine the association between Cdx2 and common clinicopathological features of gastric cancer as well as 5-year survival rate, and to consider the significance of Cdx2 expression in the prediction of outcome in gastric cancer." (PMID 23181722, 2012). "However, Xiao and colleagues showed that there was not association between Cdx2 expression and lymph node metastasis of gastric carcinoma." (PMID 23181722, 2012). "Loss of CDX2 may represent a marker of tumor progression in early gastric cancer and carcinomas with an intestinal, but not a non-intestinal phenotype." (PMID 16539725, 2006). "These additional signals may also play a role in gastric carcinomas, given that WNT/APC/β-catenin pathway-activated mutations are not universally observed in CDX2-induced gastric cancers and are observed in lower frequency in the sub-set with SOX2-expression maintenance." (PMID 40149431, 2025). "Overexpression of miRNA-9 and miRNA-326 is correlated with gastric cancer carcinogenesis, which targets caudal type homeobox 1 (CDX1) and CDX2 (tumor suppressors) by promoting hypermethylation of the promoter region of CDX1 and CDX2." (PMID 36765652, 2023). "In gastric cancer (GC), intestinal metaplasia (IM) is a common precursor lesion, but its relationship to the MUC2/MUC5AC/CDX2 axis is not completely understood." (PMID 37240039, 2023).
gastric cancer (continued). "However, another study showed that CDX2 overexpression suppressed cell migration and invasion in MGC-803 cells and that CDX2 silencing promoted migration and invasion in NCI-N87 cells, indicating that CDX2 may inhibit migration and invasion of gastric cancer cells." (PMID 33639844, 2021). "Additionally, CDX2 may be an upstream regulator of Reg IV expression in gastric cancer." (PMID 33639844, 2021). "The study showed that miR21 expression of gastric cancer cells increases when cells are treated with DCA, leading to SOX2 expression suppression and the simultaneous induction of CDX2 expression under BA treatment." (PMID 34638550, 2021). "When this peptide was administered to mice with stomach cancer, a YAP/TEAD complex was observed along with a decreased expression of the genes CTGF, CYR61, and Caudal Type Homeobox 2 (CDX2)." (PMID 35008857, 2021). "Thus, CLDN4 might play a role in integrin signaling, or in CD44 associated with stemness in undifferentiated/CDX2-negative gastric cancer." (PMID 31040910, 2019). "Studies on cancer cells, including human colorectal carcinoma cells (HT-29), human colon adenocarcinoma cells (Caco-2) and gastric cancer cells (BGC-823), demonstrated that CDX2 inhibits cell proliferation." (PMID 29156556, 2017). "Clinical history, histological findings, and immunohistochemical markers such as CK20, CK7, CDX-2, villin, and GCDFP-15 are helpful in distinguishing primary breast cancer from breast metastasis of gastric cancer." (PMID 25890325, 2015). "In this study we characterized the expression of the transcription factor SOX2 in gastric cancer and related it with clinicopathological features and differentiation markers namely MUC5AC (gastric marker) and CDX2 and MUC2 (intestinal markers)." (PMID 25300947, 2014). "In the present study, we investigated whether CDX2 regulates Reg IV expression in gastric cancer (GC) cells." (PMID 23133598, 2012). "In that case, a clinical translation of CDX2 and SOX2 as biomarkers of potentially targetable sub-sets of gastric cancers would be more straightforward, given that the infrastructure for IHC performance and evaluation exist widely in clinical pathology laboratories." (PMID 40149431, 2025). "The master regulator of HLA class II antigens CIITA and both variant and invariant HLA class II chains displayed a decreased mRNA expression in CDX2-induced gastric cancers compared with gastric cancers with no CDX2 induction." (PMID 40149431, 2025). "On the other hand, the group of gastric cancers with CDX2 and HNF4A induction had lower prevalence of MSI and no cases with EBV association." (PMID 39768557, 2024). "Moreover, recombinant Helicobacter pylori SlyD can induce CDX2 expression and activity in the gastric mucosa in a TCTP-dependent manner, thereby facilitating the development of gastric cancer." (PMID 38835077, 2024). "In gastric cancers, expression of the Hippo pathway transcription factors YAP1 and TEAD was up-regulated in parallel with CDX2, while the negative regulators of the pathway, serine/threonine kinases MST1 and LATS1, were down-regulated, compared with normal gastric epithelia." (PMID 39768557, 2024). "Further investigation into the mechanism of TCTP involvement in gastric cancer revealed that CDX2 was not expressed in normal gastric mucosal tissue but is highly expressed in gastric cancer." (PMID 38835077, 2024). "Treating gastric cancer cell lines (AGS and MKN4) with SFN led to the decreased proliferation, apoptosis induction, and reduced expression of miRNA-9 and miRNA-326, and thereby, SFN enhanced levels of CDX1 and CDX2 in AGS and MKN4." (PMID 36765652, 2023). "In addition, CDX2 overexpression promoted the development of MDR in SGC-7901/DDP (cisplatin-resistant) and BGC-823/5-FU (5-fluorouracil-resistant) human gastric cancer cells in vitro and in vivo." (PMID 33639844, 2021). "Most of the other colorectal and gastric cancer markers such as CDX2, MUC1, MUC2, and MUC6 were also negative." (PMID 34397857, 2021).
gastric cancer (continued). "Reports have shown that CDX2 expression is related to IM of the stomach, lymphatic metastasis, survival, cell proliferation, migration, invasion, and multidrug resistance (MDR) in gastric carcinoma." (PMID 33639844, 2021). "Thus, in initial studies, we evaluated CDX2 expression and the expression of another epithelial cell differentiation marker, VIL1, in human gastric cancer cell lines before and after treatment with HpSlyD." (PMID 28536478, 2017). "The over-expressed miR-9 might target CDX2 via its binding site in the 3′-UTR, resulting in the promotion of cell proliferation in gastric cancer." (PMID 28178677, 2017). "MiR-9 expression was up-regulated in bladder transitional cell carcinoma, mixed lineage leukemia-rearranged acute myeloid leukemia, hepatocellular carcinoma, primary brain tumors, CDX2-negative gastric cancer cells and breast cancer." (PMID 27705935, 2016). "In invitro experiments, H. pylori infection induces CDX2 expression in the AGS gastric carcinoma cell line, but not in other cell lines." (PMID 27384681, 2016). "Previous studies have demonstrated that miR-9 is overexpressed in CDX2-negative primary gastric cancers and miR-9 knockdown inhibits proliferation of human gastric cancer cell lines." (PMID 24517413, 2014). "The presence of both significant and non-significant studies addressing the importance of Cdx2 in gastric cancer made it necessary to find a quantitative aggregation of the survival results." (PMID 23181722, 2012). "These distinct regulatory programs suggest that gastric cancers should not be treated as a uniform entity; rather, location-specific biomarkers like CDX2 or GATA6 could potentially inform prognosis and therapeutic decisions." (PMID 40862793, 2025). "The family member ELF3 was well expressed in the mRNA level in a subset of gastric cancers (n = 91), and its expression correlated with the expression of other transcription factors involved in gastric cancer pathogenesis, including HNF4A, HNF1A, CDX2, GATA4, GATA6, and EHF." (PMID 41425714, 2025). "Despite these reverse regulations of CDX2 and SOX2, a study of gastric carcinoma has not found a reverse association of the two factors when examined by IHC staining, suggesting retained expression of both factors due to deregulation of the networks that physiologically determine tissue identities." (PMID 40149431, 2025). "Similarly to the findings from TCGA, in a series of intestinal type gastric cancers, HER2 over-expression was observed more often (50% of cases) in CDX2-positive cases than in CDX2-negative cases, where HER2 over-expression was only present in 1 of 15 (6.7%) of patients (p = 0.009)." (PMID 39768557, 2024). "Interestingly, both CDX2 and HNF4α possess binding sequences in the promoter of YAP1, and a positive feed-forward loop may be operating in gastric cancers with CDX2 induction." (PMID 39768557, 2024). "However, the regulatory roles of CDX2 have not been clarified in gastric cancer, and the correlation between CDX2 and Reg IV requires further study." (PMID 33639844, 2021). "Decreases in CLDN4 expression in undifferentiated/CDX2-negative gastric cancer might be explained as resulting from induction of the EMT phenotype." (PMID 31040910, 2019). "These researches suggested that Cdx2 did not affect the progression of human gastric cancer." (PMID 23181722, 2012). "Thus, we speculate that the aberrant expression of SOX9 may trigger negative feedback regulation on CDX2 and Reg IV in gastric cancer cells." (PMID 33639844, 2021). "CDX2 promotes MUC2 expression but is not always co-expressed; CDX2-negative/MUC2-positive gastric cancers have been reported, indicating this finding can occur in MUC2-positive gastric tumors." (PMID 39939466, 2025). "In this case, the lesions in the fundic gland polyps were positive for CK7, ER, and GATA3 and negative for CK20 and CDX2, supporting metastatic ILC and ruling out primary gastric carcinoma." (PMID 40979040, 2025).